GPX4 (glutathione peroxidase 4)
Diseases named in the same sentence as GPX4 in open-access papers (continued):
Sharing a sentence is not in itself a finding about the gene and the disease.
tumor (continued). "Furthermore, combined with glutathione peroxidase 4 (GPX4)-knockdown, inhibition of DHODH by its inhibitor, brequinar, markedly suppressed xenograft tumor growth mediated by ferroptosis." (PMID 36788244, 2023). "In addition, immunofluorescence staining using xenograft ccRCC tumor tissues showed increased localization of CX3CL1; GPX4 and PCNA were found to have decreased expression in the OE-CX3CL1 group compared to that in the control group." (PMID 36397015, 2022). "Our study implies that ferroptosis may take place in GBM tumor cells due to the profound changes in the expression of ACSL4 and GPX4." (PMID 35530303, 2022). "Overexpression of FTL, GPX4 and NUPR1 in UCA1+ EPCAM+ cells suggests these key genes may be upregulated further along the RMC oncogenic program to increase protection of the tumor against cell death induced by ferroptosis." (PMID 35837094, 2022). "Nearly 12% of cases showed IDH1105GGT single nucleotide polymorphism, which was never described in ICC up to now, and was related to lower tumor grade (p < 0.0001), longer overall survival (p = 0.04), and lower GPX4 levels (p = 0.001)." (PMID 35872783, 2022). "A previous study in TNBC to investigate the role of GPX4 played in ferroptosis and apoptosis indicated that GPX4 was remarkably increased in TNBC tissue other than non-TNBC tissue and associated with tumor stages." (PMID 36276158, 2022). "Statistical analysis did not reveal any significant differences in both the GPx4 and GPx8 groups with regard to the quantity of expression, age, gender, tumor grade, histotype or regional lymph node lesion." (PMID 35208621, 2022). "It is worthy to note that Treg-specific ablation of GPX4 compromises survival of intratumoral Tregs without affecting splenic Tregs from the tumor-bearing mice." (PMID 35720275, 2022). "The reduction in the expression levels of NRF2, GPX4, HO-1, and FTH1 by caryophyllene oxide also inhibited GSH and hydroxyl radical’s inhibitory capacities in serum, and promoted iron deposition in tumor tissue resulting in the inhibition of tumor growth." (PMID 35899120, 2022). "Importantly, the combination of GPX4 inhibition and NRF2 silencing efficiently eradicated the tumor cells within spheroids, highlighting the potential for dual targeting of NRF2 and ferroptosis in solid tumors." (PMID 35065965, 2022). "Furthermore, glutathione peroxidase 4 (GPX4) is a key regulator of ferroptosis, its silencing leads to selective persister cell ferroptosis in vitro and prevents tumor recurrence in mice." (PMID 36352396, 2022). "A recent study demonstrated that Wnt/NR2F2/GPX4 promoted acquired chemoresistance by suppressing ferroptosis with high consumption of GSH, and also revealed the key role of NR2F2 in the regulation of tumor metabolism." (PMID 36465351, 2022). "Supportively, we also provided an A549 sh-GPX4 xenograft tumour model to consolidate a negative correlation between ferroptosis and radioresistance." (PMID 36050447, 2022). "Moreover, drug-resistant tumor cells are more sensitive to lipid peroxidation, and inhibitors of the System Xc−/GSH/GPX4 axis have been shown to be fatal in host cells." (PMID 36105219, 2022). "In addition, FINs targeting GPX4, such as RSL3 and ML162, can enhance the radiosensitivity of tumor cells." (PMID 36176274, 2022). "Subsequently, western blot showed that the expression levels of E-cadherin and HO-1 were notably enhanced by Lut or erastin, whereas MMP2, vimentin, GPX4, and SLC7A11 expression levels in tumor tissues treated with Lut or erastin were remarkably inhibited compared with those in the controls." (PMID 35656025, 2022). "First, the current study (like several previous studies) used genetic ablation of GPX4 as the approach to inhibit GPX4 in tumours, because currently there is no good GPX4 inhibitor available that is suitable for in vivo treatment." (PMID 35908258, 2022).
tumor (continued). "In addition, Serine and arginine rich splicing factor 9 (SFRS9) can upregulate the expression of GPX4 by binding to GPX4 mRNA, which promote the growth of CRC, while SFRS9 knockdown significantly inhibited tumor growth in nude mice." (PMID 36105219, 2022). "Down-regulation of GPX4 and LPO clearance elicit the ferroptosis in tumor cells." (PMID 36467032, 2022). "The nanoparticles would depolymerize because of the high GSH expression in the tumor microenvironment (TME), and the activated cinnamaldehyde (CA) could consume GSH and down-regulate GPX4." (PMID 36274142, 2022). "However, another study found that GPX4 suppressed the formation and progression of HCC by inhibition of angiogenesis and tumor cell proliferation as well as by immune-mediated mechanisms." (PMID 35659304, 2022). "As expected, high levels of GPX4 and xCT expression were clearly observed in tumor tissues compared with noncancerous tissues." (PMID 35978266, 2022). "The IHC score of GPX4 expression was also significantly increased in EC tumor tissues than the noncancerous counterparts." (PMID 35962333, 2022). "GPX4 overexpression inhibited ferroptosis in CD8 + T cells and restored the production of cytotoxic cytokines in vitro, simultaneously increasing the quantity of cancer infiltrative CD8 + T cells in vivo, which enhanced tumor control." (PMID 36335094, 2022). "The evidence supporting the role of FRGs in tumor immunity also arises from the study that T cells lacking GPX4 failed to expand and they rapidly underwent ferroptotic cell death." (PMID 33969928, 2021). "After efficient internalization into cancer cells, Mn-MOF persistently catalyzed tumor-overexpressed H2O2 to in-situ produce O2 to relieve tumor hypoxia and decrease GSH and GPX4, which facilitated the formation of ROS and ferroptosis to kill cancer cells upon US irradiation in hypoxic tumors." (PMID 33408790, 2021). "The expression of FSP1 is positively associated with the resistance of cells to GPx4 inhibitors, and FSP1 is essential to maintain tumor cell growth in the absence of GPx4." (PMID 34611144, 2021). "Although a previous study reported that GPX4 could prevent Treg cells from lipid peroxidation and ferroptosis, whether SLC7A11, GPX4, and AIFM2 participated in the regulation of ferroptosis of other immune cells and tumor progression is still largely unknown." (PMID 34722530, 2021). "In summary, SLC7A11, GPX4, and AIFM2 are dysregulated in many types of cancers, and are candidate prognostic biomarkers for many types of cancers, and can be used to evaluate the infiltration of immune cells in tumor tissues." (PMID 34722530, 2021). "Our results suggest that SLC7A11, GPX4, and AIFM2 are dysregulated in many types of cancers, and are candidate prognostic biomarkers for many types of cancers, and can be used to evaluate the infiltration of immune cells in tumor tissues." (PMID 34722530, 2021). "To test whether a combination effect can be observed using other GPx4 inhibitors in an MTDH-dependent manner, and to prevent tumor growth, we replaced RSL3 with ML162." (PMID 31527591, 2019). "As we observed that the GPx4 inhibitors ML162 and ML210 enhanced the tumor killing effect of the system xc− inhibitor sorafenib in vitro, we explored whether a similar effect could be observed in vivo." (PMID 31527591, 2019). "As GSH can directly scavenge radicals, high glutathione content inhibited tumor cell proliferation in rat HCC model and might thus contribute to the anti-proliferative GPx4 effects." (PMID 29515790, 2018). "We speculate that increased levels of GPX4 and MPND in primary cancer may facilitate tumor growth and progression." (PMID 26330360, 2015). "However, the therapeutic potential of both pathways is significantly hindered by the tumor microenvironment (TME), where elevated levels of GSH and GPX4 efficiently neutralize reactive oxygen species (ROS) and lipid peroxides, thereby attenuating ferroptosis and cuproptosis." (PMID 41476754, 2026).
tumor (continued). "Furthermore, exploiting antioxidant vulnerabilities through aldehyde dehydrogenase (ALDH) inhibition with agents like disulfiram, or glutathione peroxidase 4 (GPX4) inhibition, can induce ferroptosis specifically in DTP populations, further reducing residual tumor burden." (PMID 40894234, 2025). "The results demonstrated that the protein and mRNA levels of NFE2L1 and GPX4 were significantly increased in tumor tissues, whereas the ferroptosis marker proteins PTGS2, and CHAC1 were expressed at low levels in tumor tissues, however, SLC7A11 exhibited significant overexpression in tumor tissues." (PMID 41189569, 2025). "Similarly, exosomal ferroptosis-related protein markers (GPX4, ACSL4) and lipid peroxidation products (4HNE) may also reflect tumor cell ferroptosis activity and serve as potential tumor diagnostic tools." (PMID 40328736, 2025). "In addition, the inactivation of GPX4 triggered by FG-CDs@Cu enhances the sensitivity of tumor cells to IFN-γ and TNF-α, forming a “positive ferroptosis-immunity cycle”, which reduced the tumor volume by 67% in a model of lung metastasis of melanoma." (PMID 40559667, 2025). "Additionally, Ki‐67 immunostaining demonstrated significantly reduced proliferative activity of tumor cells, and no significant glutathione peroxidase 4 (GPX4) expression differences across groups ruled out ferroptosis as a dominant mechanism." (PMID 41014626, 2025). "Agents target certain mitochondrial processes, such as GPX4, DHODH, iron metabolism pathway, etc., to increase intracellular oxidative stress or attenuate the ferroptosis defense system, thereby inducing the ferroptosis of tumor cells and blocking tumor cell growth." (PMID 40083691, 2025). "In consistent with these in vitro results, GPX4 and FSP1 levels were sufficiently reduced after CAP treatment, elevated in mice tumor samples carrying EGFR(Y1068F) mutation, and non-distinguishable in the 'EGFR(Y1068F)+CAP' group as compared with the control (mice inoculated with SUM159PT cells)." (PMID 39781456, 2025). "It is plausible that triple combined blockade of GPX4, ALK, and activated bypass signals may be a potent therapeutic strategy for patients with ALK+ NSCLC to prevent the development of drug resistance, and lead to tumor eradication." (PMID 39369284, 2025). "Interestingly, pharmacological inhibition of GPX4 selectively induces ferroptosis in CD8+ T cells without significantly affecting tumor cell viability." (PMID 40919133, 2025). "Proteogenomics and transcriptomics have identified ferroptosis-related gene networks (e.g., GPX4, SLC7A11, ACSL4) as predictors of immunotherapy responsiveness, while single-cell RNA sequencing has revealed heterogeneity in ferroptosis sensitivity across tumor and immune subsets." (PMID 41562065, 2025). "Interestingly, previous studies have shown that GPX4 expression in cancer and immune cells in the tumor microenvironment (TME) is not uniform, but rather exhibits different immunosuppressive or immunoenhancing functions depending on the context 15,16." (PMID 40365295, 2025). "In addition, tumor tissues were analyzed using immunohistochemistry, and these results showed that GluOC reduced the expression levels of PTEN but increased the expression levels of P-PIK3CA, P-AKT, Nrf2, SLC7A11, GPX4, and SLC38A1." (PMID 40075587, 2025).
tumor (continued). "However, whether CTRP6 functions as a general ferroptosis suppressor—by regulating both the SOCS2–xCT/GPX4 and GRP78–MAMs pathways—or acts in a tumor-type–specific manner remains to be determined." (PMID 41228203, 2025). "Moreover, heightened GPX4 expression correlates with a significant upregulation of M2 macrophage markers (VSIG4 and MS4A4A), indicating a possible function for ferroptosis in influencing immune cell polarization in the tumor microenvironment." (PMID 40687837, 2025). "For example, circBCAR3 promotes tumor proliferation by sponging miR-27a-3p; TMEM161B-AS1 modulates ferroptosis via the miR-27a-3p/GCH1 axis; ARHGEF26-AS1 promotes ferroptosis through the miR-372-3p/ADAM23 pathway; and circPVT1 regulates GPX4 and SLC7A11 expression via the miR-30a-5p/FZD3 axis." (PMID 41293165, 2025). "The immunosuppressive properties of the tumor microenvironment (TME) further limit its efficacy: regulatory T cells (Tregs) suppress ferroptosis by consuming cysteine and secreting IL-10, while tumor cells escape through the Nrf2 pathway by upregulating GPX4 and FSP1." (PMID 40535125, 2025). "Moreover, FSP1 operates independently of the GPX4–GSH system, suggesting that co-targeting FSP1 and GPX4 may synergistically trigger ferroptosis and circumvent tumor cell survival mechanisms." (PMID 41185600, 2025). "The System Xc–/GSH/GPX4 axis, DHODH–ubiquinol (CoQH2) system, FSP1–CoQ10 axis, GTP cyclohydrolase-1 (GCH1)–tetrahydrobiopterin (BH4) axis, and sex hormones can inhibit ferroptosis, and the inhibition of related molecular pathways is an important strategy to induce ferroptosis in tumor cells." (PMID 39399506, 2024). "Interestingly, the combination treatment of Eto and IKE blocked MDSCs’ immunosuppressive function and accumulation by downregulating the expression of SLC7A11, GPX4, and ARG1 while promoting T-cell proliferation and infiltration into tumor tissues to enhance cancer therapy." (PMID 39596904, 2024). "Therefore, targeting molecules such as GPX4 and SLC7A11 to induce ferroptosis may provide a promising strategy to overcome tumor resistance and offer a new avenue for cancer treatment." (PMID 39771583, 2024). "The activation of GSK3β and decrease of GPX4 expression induced by CO were also not observed after NAC treatment, indicating that ROS might be the primary cause of tumor-cell ferroptosis in response to CO treatment." (PMID 38263152, 2024). "Among other oncogenes contributing to tumor initiation and progression, PI3K has been revealed to induce the activation of mTOR complex 1 (mTORC1), which is responsible for the inhibition of the ferroptotic pathway through different mechanisms, including an increase in GPX4 protein synthesis." (PMID 38539554, 2024). "Importantly, Gi-F exhibits substantial inhibition of GPX4 activity by assembly enhanced binding (AEB) effect, augmenting the oxidative stress of ferriporphyrin-based Fenton reaction, ultimately enabling antitumor properties in multiple tumor models." (PMID 38212623, 2024). "In addition, some proteins can stimulate tumor cells to switch from oxidative phosphorylation (OXPHOS) to glycolysis, in turn leading to lower levels of GSH, which suppress the activity of GPX4 and boost the accumulation of lipids, thus resulting in ferroptosis." (PMID 38459004, 2024). "Thus, FeS2@CP-based CDT efficaciously killed the tumor cells by initiating a dual cell death mechanism of apoptosis and ferroptosis, which was mediated by both LPO due to large amounts of •OH production and GPX4 inactivation due to GSH depletion." (PMID 38561739, 2024). "In fact, at the baseline, KL tumors exhibited a lower amount of GPX4 compared to K tumors and, the treatment with metformin and caloric restriction (CR) led to a further decrease in GPX4 levels that was more pronounced in tumor lacking LKB1." (PMID 38163906, 2024).
tumor (continued). "With the deepened comprehension of molecular mechanism, glutathione peroxidase 4 (GPX4) has been thoroughly reported as a key regulator for protecting cells from toxic lipid hydroperoxides of ferroptosis, which is highly expressed in tumor tissues compared with that in adjacent normal tissues." (PMID 38212623, 2024). "Emerging evidences have indicated that the activation of ferroptosis by GPX4 inhibitors (such as peptide GACNWLPLYPCPV6, derived by screening peptide libraries displayed on T7 phages) is increasingly recognized as a prominent therapeutic strategy for tumor suppression." (PMID 38212623, 2024). "In comparison to the control group, the ferroptosis-related proteins COX2, NRF2, and CD71 were upregulated, and GPX4, xCT, FTH1, and FLCA were downregulated dose-dependently in the uridine-treated group, indicating that uridine could inhibit HCC tumor growth in vivo via the induction of ferroptosis." (PMID 37240659, 2023). "In the mechanism of tumor development and metastasis in the digestive system, ferroptosis-related circRNAs interacts with miRNA to regulate downstream target substances and changes GSH content through the Xc-system to affect GPX4 or directly change GPX4 activity." (PMID 37168995, 2023). "Importantly, although spXmm66 is derived from a BAP1+/non-monosomy 3 (D3) tumor it highly expresses GPX4, explaining its strong response to RSL3." (PMID 37321991, 2023). "Although targeting GPX4 alone may not achieve optimal anti-tumor effects, simultaneous deletion of both GPX4 and FSP1 has shown promise in effectively reducing tumor growth." (PMID 37371948, 2023). "Furthermore, we examined the expression level of the PD‐L1 and GPX4 proteins in the TVGH HNSCC tumor samples, and a significant negative correlation between PD‐L1 and GPX4 was revealed." (PMID 37026630, 2023). "Our data indicated that the levels of antioxidants (such as SOD1, Gpx4) in the TME of HFD-fed mice might be insufficient to protect the cells from autophagy and apoptosis during the process of tumor development, at least during the early time point after tumor implantation." (PMID 36675341, 2023). "However, it is unclear whether tumor cells affect CD8+ T cells, directly or indirectly, through other immune cells after GPX4 knockdown." (PMID 37649598, 2023). "Similarly, combined inhibition of CAIX and GPX4 using the ferroptosis inducer RSL3 synergistically enhanced ferroptosis and co-targeting of CAIX activity and GSH synthesis in vivo decreased tumour growth and increased survival through a ferrroptosis-mediated mechanism." (PMID 38099193, 2023). "Combination therapy with GPX4 inhibitors and anti-PD1 resulted in better tumor suppression and remodeling of tumor microenvironment (TME) compared with monotherapy, suggesting that the combination strategy could be effective in treating tumors with similar biological characteristics to LAR." (PMID 37928550, 2023). "Interestingly, RCC cells were more sensitive to erastin-induced ferroptosis than others tumor cell types, which might be attributed to the dependence of GSH content and GPX4 activity to regulate redox homeostasis." (PMID 37064095, 2023). "Moreover, other ferroptosis marker genes were differentially affected by erastin and IKE in tumor tissues; specifically, prostaglandin-endoperoxide synthase 2 (PTSG2) was significantly increased, whereas glutathione peroxidase 4 (GPX4) was decreased by erastin or IKE." (PMID 36967385, 2023). "Notably, the expression levels of SLC7A11 and GPX4 were related to tumour diameter and distant metastasis but not to age, sex, lymph node metastasis, or pathological differentiation." (PMID 37807410, 2023).